ENSG00000292271 (T cell receptor beta diversity 2)
Synonyms: TCRBD2; TRBD2
Gene: T-cell receptor diversity (D) gene on chromosome 7 (142,795,705 to 142,795,720, forward strand). Ensembl gene ENSG00000292271.
Diseases named in the same sentence as ENSG00000292271 in open-access papers:
ENSG00000292271 is named in the same sentence as 2 diseases in open-access papers, as found by Europe PMC text mining. Sharing a sentence is not in itself a finding about the gene and the disease.
ENSG00000292271 shares sentences with these, for which no sentence is quoted: COVID-19 (1 paper); infection (1).